SOX2 (SRY-box transcription factor 2)
Diseases named in the same sentence as SOX2 in open-access papers (continued):
Sharing a sentence is not in itself a finding about the gene and the disease.
cancer (continued). "For example, owing to the presence of oncogenes such as c-Myc, KLF4, and SOX2, pluripotent cancer cells possess safety concerns in oncogenesis due to aberrant differentiation." (PMID 31464654, 2019). "Accumulating evidence suggests that transcription factor SOX2 is a key regulator in the plasticity of cancer stemness." (PMID 31552166, 2019). "By Western blot, all cancer-derived colonies and most of those derived from benign thyroid lesions or collateral normal thyroid tissue expressed Oct-4 and Sox-2 protein." (PMID 31431834, 2019). "Sox2 is an important embryonic stem cell marker, and it has been shown to promote cancer stemness in a large number of human cancer models, including breast, gastric, ovarian, prostate and lung." (PMID 29401647, 2018). "It has also been found that the reprogramming transcription factors OCT4 and SOX2 are highly expressed in undifferentiated cancer stem cell subpopulations and play an important role in the maintenance of the stem phenotype of cancer stem cells." (PMID 30344611, 2018). "One of the important aspects of this current study is highlighted by the observation that Sox2 phosphorylation can be modulated in response to oxidative stress, a stimulus previously shown to increase cancer stemness." (PMID 29401647, 2018). "CAGE directly regulates SOX-2 expression and cancer stem cell-like properties in anti-cancer drug-resistant melanoma cells." (PMID 30619741, 2018). "Considering the broad diversity of cancers expressing Sox2, the functions and downstream targets of Sox2 are likely to be relevant for other cancers." (PMID 29899857, 2018). "Our results have further substantiated the importance of the Wnt/β-catenin/MYC/Sox2 axis in conferring the cancer stem-like phenotype in ALK+ALCL." (PMID 29609590, 2018). "More investigations showed higher level of stem cell (NANOG, OCT4, SOX2) and cancer stem cell (CD44 and ALDH1) markers in BORIS-positive cells in comparition to BORIS-negative cancer cells." (PMID 30323717, 2018). "Recently, SOX2 is known to interact with other transcription factors to regulate gene expression not only in embryonic stem cells (ES) but also in cancer cells." (PMID 30108202, 2018). "Altogether, these findings unveil a previously unexplored role of PHGDH in the regulation of self-renewal and stemness factors (KLF4, Oct4, Nanog, Sox-2, and Lin28B) in cancer stem-like cells." (PMID 30250195, 2018). "Additional peaks involving important cancer genes such as SOX2, MYC, VEGFA and CDK6 were also found." (PMID 29370817, 2018). "In recent years, aberrant expression of Sox2 has been demonstrated in various types of human cancers, including CRC12–14." (PMID 30518951, 2018). "SP+ cancer stem cells were characterized by high expression of the transcription factors Sox2, Nanog and Oct4, high metastasizing capacity and high production of some cytokines, including IL-6 and VEGFA." (PMID 30060526, 2018). "The IL6, phosphorylated JAK2, phosphorylated STAT3 and SOX2 protein levels in 97L cancer cells were greatly elevated by SHH treatment." (PMID 29722127, 2018). "The SOX2 (sex-determining region Y-box 2) was a highly conserved transcription regulator and played a vital role in the cancer progression." (PMID 29921304, 2018). "Consistently, the expression of cancer stemness biomarkers, including SOX2 and OCT4, was decreased following the downregulation of TBX21 expression in western blot analyses." (PMID 29615105, 2018). "Patterns of concomitant expression of SOX2OT and SOX2 in stem cells and several human cancers suggest a common co‐regulation mechanism and involvement of similar molecular pathways." (PMID 30117678, 2018). "It is usually only expressed in type I GBM cancer stem cells and is co-expressed with the stem cell markers SOX2, SOX11 and OLIG2." (PMID 30208958, 2018).
cancer (continued). "The expression of transcription factor SOX2 was widely reported upregulated in multiple types of malignant tumors, thus serving as a oncogene through regulating tumorigenesis, progression, and metastasis." (PMID 30108202, 2018). "Oct4, Sox2 and c-Myc are key factors involved in the reprogramming of cancer cells into cancer stem cells." (PMID 29180117, 2018). "Wnt promotes cell growth, survival, and maintenance of stemness through the β-catenin–TCF3 complex by inhibiting the pluripotency of the factors Oct3/4, Sox2, and Nanog, thus maintaining the self-renewal capacity of cancer stem cells." (PMID 30404206, 2018). "Previous studies reported that CSC biomarkers such as NANOG, OCT4, SOX2, KLF4 and ALDH1A1 were associated with a poor prognosis in several cancers." (PMID 29615105, 2018). "SOX-2, which is a member of the SRY-related HMG-box (SOX) transcription factor family involved in several cellular processes, has been implicated in cancer development." (PMID 30227679, 2018). "Our study results also have provided further support that the Wnt/β-catenin/MYC/Sox2 axis is the key regulator of cancer stemness in ALK+ALCL." (PMID 29609590, 2018). "Our result is distinct from studies of Sox2ot in cancers, where it is found to positively regulate Sox2 expression." (PMID 30038234, 2018). "SOX2 has been identified as an oncogene that promotes squamous cancer development by promoting cancer cell viability, proliferation, migration and invasion etc." (PMID 30053878, 2018). "Our finding was further supported by western blotting, which showed that expression of cancer stem markers, Bmi1, Sox2 and Musashi1, was markedly increased by treatment with TGF-β1 and decreased by treatment with metformin." (PMID 29467947, 2018). "Aside from their ability to induce pluripotency, the Yamanaka factors (OCT4, SOX2, KLF4, and c-MYC), and other reprograming factors like NANOG or LIN28, have been widely implicated in tumorigenesis in various cancers including the prostate." (PMID 29888169, 2018). "Our results also revealed that the regulation of CSC related genes by BRACHYURY and SOX2 is different by cancer cell origin (stratified squamous epithelial cells and salivary gland cell)." (PMID 30453543, 2018). "We also tested the effect of AF and its combination with ADM on the expression of cancer stem cell markers including SOX2, Oct4, and ABCG2." (PMID 29367724, 2018). "OCT4 is a master transcription factor that regulates the pluripotency of pluripotent stem cells and cancer stem cells along with other factors, including SOX2, KLF4, and C-MYC." (PMID 30287838, 2018). "Some studies have suggested that SOX2 overexpression promotes cancer progression, suggesting that low SOX2 expression increases the survival rate of patients with cancer compared with high SOX2 expression." (PMID 29374236, 2018). "As an important cancer stem cell marker, SOX2 is involved in cell proliferation, differentiation, invasion, metastasis, drug resistance, relapse, and others processes of tumors." (PMID 30186173, 2018). "Since we investigated early neural development using non-transformed mouse cells our data indicate that Sox2 regulation during stem cell maintenance and differentiation is completely different from Sox2 regulation in cancer cells." (PMID 29321583, 2018). "While it is evident that Sox2 phosphorylation is important in regulating the transcriptional activity of Sox2 and its ability to confer cancer stemness, it remains to be determined which Sox2 residue(s) are the critical sites." (PMID 29401647, 2018). "Several members of SOX family stimulate the initiation and progression of different cancers, including SOX2 and SOX4." (PMID 29541384, 2018). "Owing to amplification on chromosome 3q26, Sox2 is frequently over-expressed in carcinomas including HNSCC30." (PMID 30275505, 2018).
cancer (continued). "In this study, we have developed a zinc finger-based artificial transcription factor (ATF) to selectively suppress SOX2 expression in cancer cells and termed the system ATF/SOX2." (PMID 29262545, 2017). "For several cancers, the levels of SOX2 expression at different stages of the cancer have been examined." (PMID 28388544, 2017). "In regard to cancer, recent studies have shown that SOX2 is amplified in various cancer types that affect cancer cell physiology including proliferation, apoptosis and resistance to standard therapies." (PMID 28636992, 2017). "This was also supported by increased expression of cancer stem cell (CSC) markers such as SOX2 and CD133 in U3333MET cells after 48-h coculture with MCs in comparison to control cells." (PMID 28626727, 2017). "Data available from The Cancer Genome Atlas indicates that SOX2 mRNA is elevated in many cancers, relative to normal tissue." (PMID 28388544, 2017). "Using multiple analyses of cancer cells and tumorspheres, we observed SOX2 was the most consistently altered factor with the highest magnitude of change when NFATc2 expression or calcineurin activity were manipulated." (PMID 28737489, 2017). "The reasons for the contrasting results for SOX2 levels in different cancers remain to be determined." (PMID 28388544, 2017). "One of the common properties of CD44v3highALDH1high CSCs isolated from HNSCC is the upregulation of cancer stem cell markers (e.g., Nanog, Sox2 and Oct4) which are known to function as transcriptional factors." (PMID 28837080, 2017). "Consistently, AURKA knockdown downregulated the expression of FOXM1 and that of the cancer stem cell markers c-Myc, SOX2 and Nanog in MDA-MB-231 cells." (PMID 28114286, 2017). "The excitement surrounding the key roles of Sox2 in ESC and iPS cells, which are themselves tumorigenic, soon led to the search for SOX2 in cancer." (PMID 28388544, 2017). "Accordingly, aberrant SOX2 expression was detected in multiple types of cancers at different stages." (PMID 28288641, 2017). "SOX2 was identified as an oncogenic factor and was reported to be overexpressed in certain types of cancer." (PMID 29104726, 2017). "Consistently, FOXM1 knockdown downregulated the expression levels of cancer stem cell markers SOX2, c-Myc and Nanog, and reduced the mammosphere formation capacity and the CD44hi/CD24lo population in MDA-MB-231 cells." (PMID 28114286, 2017). "Significantly lower SOX2 (P < 0.05) RNA level were detected in cancer tissues compared with adjacent tissues." (PMID 29296232, 2017). "Rep-H103 expressed the pluripotency markers of Oct4, Sox2, Nanog and Tra-1-60 indicating a distinct difference between H103 derived iPS-like cells over its parental cancer cell line." (PMID 28417059, 2017). "Addressing these questions is expected to lead to new insights into the functions of SOX2 in cancer, which will help design novels strategies for more effectively treating some of the most deadly cancers." (PMID 28388544, 2017). "Recently, it has been shown that a stem cell transcription factor (Sox2) supports cancer stem cells through the inhibition of the Hippo pathway." (PMID 28531111, 2017). "Altogether, our results indicate that overexpression of CD109 in SCC cells led not only to a reduction in EMT marker expression, but also to a decrease in Sox2 expression and spheroid formation, indicating a reduction in the cancer stem cell population." (PMID 29221155, 2017).
cancer (continued). "Regarding that OCT4 and Sox2 are specific markers cancer stem cells (CSC), we for the first time revealed that CD8+ CIK cells are able to recognize CSC specific antigens." (PMID 28426690, 2017). "Within a few years after the discovery of iPS cells, numerous reports of SOX2 expression in human cancer had already appeared." (PMID 28388544, 2017). "In cancers where aberrantly reactivated, SALL4 has been associated with the expression of many stemness-related genes (i.e. OCT4, NANOG, c-Myc, and SOX2) conferring to the cancer cells self-renewal pluripotency abilities." (PMID 28160555, 2017). "This also led us to infer that although prominently known to be one of the key promoters of EMT and invasiveness in a number of cancer types, the role of SOX2-dependent TWIST1 in maintaining stemness was more prominent when SOX2 expression was high in brCSCs." (PMID 28835684, 2017). "WB analysis showed that the Sox2 expression levels were significantly higher in cancer tissues than that in the normal counterparts." (PMID 29228716, 2017). "With the purpose of better understanding the effects of cancer cells on hASCs' stemness setting, RT-PCR analyses were performed for stemness genes, including Sox2, Nanog and OCT3/4." (PMID 28102844, 2017). "Overall, the data indicated NFATc2 induces TIC, cancer initiating phenotypes and drug resistance through upregulating SOX2 expression." (PMID 28737489, 2017). "Most importantly, the expression of stem cell markers such as Nanog, Sox2 and Oct4 is closely associated with HNSCC patient’s prognosis, pathological stages, cancer recurrence and therapy resistance." (PMID 28837080, 2017). "Regarding to SOX2, a putative cancer stem-like cell/cancer-initiating cell marker for several human malignancies, it was found down-regulated in the specimens obtained from lymph node positive OSCC." (PMID 29285222, 2017). "Similar to NFATc2, SOX2 was also upregulated in A549 induced for cisplatin resistance (A549 CR) but on NFATc2 knockdown, SOX2 levels were repressed, suggesting NFATc2/SOX2 coupling was functionally active in resistant cancer cells." (PMID 28737489, 2017). "Close concomitant expression patterns of SOX2OT and SOX2 in stem cells and some human cancers, have also highlighted the possibility that transcriptional regulation of SOX2 by SOX2OT." (PMID 28489861, 2017). "That SOX2 plays an important role in chemo-resistance of cancer stem cells was further demonstrated by chemo-sensitivity assays of control and silenced spheres, which were exposed to different concentrations of Pax." (PMID 28835684, 2017). "Another group also reported that miR-140/SOX2/SOX9 axis regulates cancer stem cells in early breast cancer." (PMID 29162923, 2017). "The identification of the stem-like cell population based on their differential responsiveness to the Sox2 reporter has been demonstrated in a number of cancer models." (PMID 29203817, 2017). "Although SOX2 expression has been reported in many cancers, the percent of SOX2-positive cells within SOX2-positive tumors has not been consistently reported." (PMID 28388544, 2017). "Furthermore, real-time PCR analysis showed knockdown of lncRNA XIST could markedly decrease the expression of many stemness-associated genes (Nanog, Oct-4 and SOX2) and surface antigens associated with cancer stem cells (CD24, CD44, CD133, CD155 and CD166) (*P<0.05)." (PMID 28837144, 2017). "We then examined another property of cancer stem-like cells, which is the expression of stem-cell markers Oct4, Sox2, and Nanog, after stimulation with GDF15." (PMID 28206960, 2017). "SOX2 expression is increased in several types of cancers, such as lung, breast, ovarian, prostate cancers." (PMID 28460458, 2017). "A recent study showed that LSD1 inactivation induces a global increase of both mono- and dimethylation of H3K4 and mono- and dimethylation of H3K9 in Sox2-expressing cancer cells." (PMID 28121627, 2017).
cancer (continued). "In the current study, one cell expressing KRT14 was found among SOX2-positive cancer cells in the E-side." (PMID 29079795, 2017). "Nonetheless, it is evident from the impressive body of work published thus far that SOX2 is a major player in cancer and a potential therapeutic target." (PMID 28388544, 2017). "Stem-like NB cells were purified based on their responsiveness to a Sox2 reporter, a strategy previously used for several different cancer models." (PMID 29203817, 2017). "OCT4, Sox2 and Nanog are basic transcriptional factors that are expressed in cancer stem cells as well as in embryonic stem cells." (PMID 28380428, 2017). "The number of cancer cells passing through the filter of the transwell are significantly reduced after SOX2 knockdown (p < 0.01 for ZR7530 and p < 0.05 for MDA-MB-231)." (PMID 28288641, 2017). "Since OCT4 and Sox2 are markers of cancer stem cells, it is possible CD8+ CIK cells exert anticancer effects through specific TCR to recognize cell surface HLA-antigen peptide complex." (PMID 28426690, 2017). "In the final section of this review, Conclusions and Future Perspectives, we discuss several important questions that remain unanswered concerning the roles of SOX2 in cancer." (PMID 28388544, 2017). "This review provides a comprehensive overview of the roles of SOX2 in cancer and focuses on two broad topics." (PMID 28388544, 2017). "Analysis on a database cohort validated the correlation between Sox2 expression and poor prognosis in stage II cancer." (PMID 28046028, 2017). "It was also found that cells with SiRb‐OeMyc increased the ability to form spheres in TSM, the in vitro culture medium for cancer stem cells 34 and expressed pluripotency genes, such as Oct4, Nanog, and Sox2, both before and after culture in TSM." (PMID 28191765, 2017). "The search terms “SOX2 and cancer” generate over 1,600 hits in the PubMed database and over 11,000 hits in PubMed Central." (PMID 28388544, 2017). "The discussion in the previous section deals with an important property of SOX2 in cancer: its levels must be carefully controlled." (PMID 28388544, 2017). "For most cancers, SOX2 expression has also been documented at the protein level by immunohistochemistry." (PMID 28388544, 2017). "Western blot assay and immunofluorescence assay showed that tunicamycin obviously reduced the expression of Sox2, a key gene sustaining self-renewal of normal and cancer stem cell." (PMID 27119230, 2016). "In recent years, aberrant expression of SOX2 has been reported in CRC as well as several other types of cancers." (PMID 27411517, 2016). "Transfection of EWS/FLI1 into mesenchymal stem cells (MSC) revealed that EFTS cancer stem cells (CSC) express genes associated with embryonic stem cell (ESC), including SOX2, OCT4 and NANOG." (PMID 26969300, 2016). "Recent studies in many cancers have concluded that the stem cell transcription factor SOX2 is likely to contribute to drug resistance." (PMID 27145457, 2016). "Recently, aberrant expression of Sox2 has been found in a relatively large number of cancer types, including breast cancer, melanoma, and ALK + ALCL." (PMID 27821172, 2016). "Does O-GlcNAcylation control the activity of SOX2 in other cell types, such as neurons and cancer cells, in which this modification can be detected on SOX2?" (PMID 26949256, 2016). "These transformed cells gained the phenotype of cancer stem cells or progenitor cells as they express pluripotency maintaining factors (Nanog, Oct-4, Sox-2 and c-Myc)." (PMID 27472393, 2016). "We also found SOX2-positive cancer cells were higher in the MDA-MB-231 tumors when compared to the MDA-MB-231-2A2 tumors." (PMID 27029061, 2016). "The functional involvement of Oct4 and Sox2 in miR-145-mediated cancer stemness and EMT in AOE cells was further clarified through Oc4/Sox2 overexpression." (PMID 27557511, 2016).